ATF1 (activating transcription factor 1)
Description:
This protein binds the cAMP response element (CRE) (consensus: 5'-GTGACGT[AC][AG]-3'), a sequence present in many viral and cellular promoters. Binds to the Tax-responsive element (TRE) of HTLV-I. Mediates PKA-induced stimulation of CRE-reporter genes. Represses the expression of FTH1 and other antioxidant detoxification genes. Triggers cell proliferation and transformation.
Synonyms: TREB36; EWS-ATF1; FUS/ATF-1
Tractability: Small molecule: it belongs to a druggable protein family. PROTAC: UniProt records ubiquitination sites on it; ubiquitination databases record sites on it; its protein half-life has been measured; a small molecule that binds it is known.
Target class: Transcription factor
Gene: Protein-coding gene on chromosome 12 (50,763,710 to 50,821,162, forward strand). Ensembl gene ENSG00000123268.
Subcellular location: Nucleus
Subcellular location (Human Protein Atlas): Nucleoplasm
Pathways (Reactome):
Signal Transduction: CREB phosphorylation; NGF-stimulated transcription
Gene Ontology:
Molecular function: DNA-binding transcription activator activity, RNA polymerase II-specific; identical protein binding; protein binding; RNA polymerase II transcription regulatory region sequence-specific DNA binding; DNA-binding transcription factor activity; DNA-binding transcription factor activity, RNA polymerase II-specific; RNA polymerase II cis-regulatory region sequence-specific DNA binding; DNA binding; protein-containing complex binding; sequence-specific DNA binding
Biological process: cAMP/PKA signal transduction; positive regulation of transcription by RNA polymerase II; regulation of transcription by RNA polymerase II; response to purine-containing compound; positive regulation of DNA replication; positive regulation of neuron projection development; protein-containing complex assembly; regulation of DNA-templated transcription; response to cobalt ion
Cellular component: ATF1-ATF4 transcription factor complex; nucleoplasm; nucleus; RNA polymerase II transcription regulator complex; ATF4-CREB1 transcription factor complex; chromatin; transcription regulator complex
Genetic constraint (gnomAD): Loss-of-function variants: 15 observed, 33.79 expected, observed/expected ratio (o/e) 0.44, 90% interval 0.3 to 0.68. The upper end of that interval is the gene's LOEUF score, 0.68, which puts it in group 2 of 6, group 1 being the genes least tolerant of losing a copy. Missense variants: 243 observed, 320.86 expected, observed/expected ratio (o/e) 0.76, 90% interval 0.68 to 0.84. Synonymous variants: 100 observed, 113.65 expected, observed/expected ratio (o/e) 0.88, 90% interval 0.75 to 1.04.
Homologues: Orthologues: chimpanzee ATF1 (99% identical), macaque ATF1 (99% identical), dog ATF1 (98% identical), pig ATF1 (97% identical), guinea pig ATF1 (95% identical), rabbit ATF1 (94% identical), rat Atf1 (92% identical), mouse Atf1 (91% identical), tropical clawed frog atf1 (73% identical), Caenorhabditis elegans crh-1 (35% identical), Drosophila melanogaster CrebB (31% identical), Drosophila melanogaster CrebA (17% identical), and 3 more. Paralogues in human: CREB1 (62% identical), CREM (56% identical), CREB3L2 (21% identical), ATF6 (20% identical), CREB3L1 (20% identical), ATF6B (19% identical), CREB3L4 (17% identical), CREB3L3 (16% identical), CREB3 (16% identical).
Diseases named in the same sentence as ATF1 in open-access papers:
ATF1 is named in the same sentence as 94 diseases in open-access papers, as found by Europe PMC text mining. Sharing a sentence is not in itself a finding about the gene and the disease. The quoted sentences say what the papers report.
clear cell sarcoma (59 papers, 2003 to 2026). A rare malignant neoplasm with melanocytic differentiation characterized by the presence of polygonal or spindle shaped clear cells. "Clear cell sarcoma (CCS) is associated with the EWS/ATF1 oncogene that is created by chromosomal fusion of the Ewings Sarcoma oncogene (EWS) and the cellular transcription factor ATF1." (PMID 12966428, 2003). "ATF1 was first associated with tumors in soft tissue malignant melanoma (clear cell sarcoma)." (PMID 35397606, 2022). "Clear cell sarcoma (CCS) is a rare soft tissue sarcoma caused by the EWS/ATF1 fusion gene." (PMID 31488818, 2019). "As an example, Mivebresib treatment was shown to reduce the protein and mRNA levels of EWSR1::ATF1 in a dose-dependent manner in clear cell sarcoma, due to the modulation of BRD4 recruitment at the EWSR1 promoter region." (PMID 41166819, 2025). "In contrast, similar to EWSR1::ATF1 fusion in clear cell sarcoma, both CRTC1::TRIM11 and MITF::CREM fusions likely lead to MITF overexpression through the induction of the CREB signaling cascade." (PMID 39264472, 2024). "Detection of EWSR1 gene rearrangement and/or confirmation of an EWSR1::ATF1 or EWSR1::CREB1 gene fusion confirms the diagnosis of clear cell sarcoma." (PMID 39264472, 2024). "The relationship between cellular histogenesis and molecular phenotypes for the EWSR1- ATF1 fusion in clear cell sarcoma (CCS) requires further characterization." (PMID 35477713, 2022). "Increased ATF1 expression was also found in patients with clear cell sarcomas in the gastrointestinal tract, T-cell lymphoma, cervical cancer, and thyroid cancer." (PMID 35397606, 2022). "For instance, EWSR1 or FUS can fuse to ATF1 or CREB1 in clear cell sarcoma of soft tissue as well as angiomatoid fibrous histiocytoma." (PMID 34081036, 2021). "The EWS/ATF1 fusion protein in soft tissue clear cell sarcoma is composed of the EAD (residues 1–325), fused to the C-terminal region of ATF1 (residues 66–271)." (PMID 25688366, 2015). "Although recurrent EWSR1::ATF1 fusions were initially limited to a triad of mesenchymal neoplasms including clear cell sarcoma of soft tissue, angiomatoid fibrous histiocytoma and malignant gastrointestinal neuroectodermal tumor (MGNET), this family has been expanding." (PMID 39031200, 2024). "The observation that EWSR1::ATF1-positive clear cell sarcomas show consistent melanocytic differentiation and expression of the melanocytic-specific MITF (MITF-M) transcript fueled the idea of the EWSR1::ATF1 fusion protein-mediated transactivation of the MITF promoter." (PMID 39769457, 2024). "This study reveals the epigenetic and transcriptional suppression mechanism of the fusion oncogene EWSR1::ATF1 in clear cell sarcoma by histone deacetylase inhibitor treatment as well as identifying SOX10 as a transcription factor that regulates EWSR1::ATF1 expression." (PMID 37405123, 2023). "As yet, the function of CREB in SySa has not been evaluated, but pathogenic translocations between EWSR1 and CREB or its homologue ATF1 in clear cell sarcoma, another fusion-driven mesenchymal neoplasia, point to a major functional role in mesenchymal tumorigenesis." (PMID 35556229, 2022). "Although little is known about the functional role of CREB in sarcomas, pathogenic translocations between EWSR1 and CREB or its homologue ATF1 in clear cell sarcoma, another fusion-driven mesenchymal neoplasia, point to a major functional role in mesenchymal tumorigenesis." (PMID 35556229, 2022). "These two forms of HEY1::NCOA2 fusion might be caused by splicing alterations, as an EWSR1::ATF1 fusion was identified in clear cell sarcoma, although we do not have any data." (PMID 39165647, 2024). "The gene fusion of activating transcription factor 1 (ATF1) and the Ewing sarcoma breakpoint region 1 (EWSR1) are pathognomonic for clear cell sarcoma, representing the key to the diagnosis." (PMID 38929464, 2024).
clear cell sarcoma (continued). "In keeping with this, TFs such as FLI1 and ATF1 acquire pioneering properties and bind otherwise-inaccessible genomic regions when fused to EWS in Ewing and clear cell sarcoma, respectively." (PMID 38275898, 2024). "Although EWSR1::ATF1 and FUS::ATF1 fusions are reported in clear-cell sarcomas and AFH,25,26 the cases herein with EWSR1/FUS::ATF1 fusions were very close to the AFH cluster, but clearly separated on the UMAP projection." (PMID 39059063, 2024). "We have recently demonstrated that the use of human embryonic stem mesenchymal progenitors (hES-MP) is important in the generation of Clear Cell Sarcoma (CCS) and Angiomatoid Fibrous Histiocytoma (AFH) models harboring the EWSR1::ATF1/CREB1 translocations." (PMID 36801905, 2023). "CREB family (CREB1, ATF1, and CREM) gene fusions are defining markers in diverse mesenchymal neoplasms (clear cell sarcoma, angiomatoid fibrous histiocytoma, and others)." (PMID 34228212, 2022). "The fusion gene of ATF1 with EWSR1 or FUS is frequently reported in sarcomas including angiomatoid fibrous histiocytoma and clear cell sarcoma, which are relatively chemoresistant." (PMID 36860287, 2021). "The two are often difficult to differentiate because 70-90% of clear cell sarcomas express melanin due to fusion of the EWS and ATF1 genes from chromosomes 22q12 and 12q13 respectively." (PMID 24274261, 2013). "In MP-CCS-SY (clear cell sarcoma), the EWS/ATF-1 fusion mRNAs were also detected, as shown in the Ewing sarcoma cell lines." (PMID 24124617, 2013). "Clear cell sarcoma (CCS), a rare but extremely aggressive malignancy with no effective therapy, is characterized by the expression of the oncogenic driver fusion gene EWSR1::ATF1." (PMID 37405123, 2023). "Interestingly, we noted that EWSR1::ATF1 oncoprotein interacted with MS0621, whereas native ATF1 did not in non-clear cell sarcoma cells." (PMID 36793594, 2023).
sarcoma (31 papers, 2012 to 2026). A usually aggressive malignant neoplasm of the soft tissue or bone. "Collectively, our results indicate that sarcoma-iPSC mice develop secondary sarcomas in a cell-type-dependent manner that is associated with the opposing senescence response to EWS/ATF1." (PMID 31488818, 2019). "Consistent with the opposing effects of EWS/ATF1 expression on senescence, Il-6, a senescence-associated secretory phenotype-associated gene was inversely regulated in sarcoma cells and sarcoma-iPSC MEFs." (PMID 31488818, 2019). "For control experiments, chimeric mice were generated with embryonic stem cells (ESCs) and iPSCs, both of which contain EWS/ATF1-inducible alleles at the identical loci as sarcoma-iPSCs." (PMID 31488818, 2019). "Here, we established induced pluripotent stem cells (iPSCs) from EWS/ATF1-controllable murine CCS cells harboring sarcoma-associated genetic abnormalities." (PMID 31488818, 2019). "While EWSR1::ATF1 and fused in sarcoma::activating transcription factor 1 (FUS::ATF1) fusion genes can be detected in AFH, they are rarely found in PPMS cases." (PMID 38421462, 2024). "Among these were epithelial carcinoma cell lines (UMRC2 and 786-O), a clear cell sarcoma cell line with the oncogenic EWS::ATF1 rearrangement (SU-CCS-1), and two primary cell lines that either express FLI1 (HUVEC) or do not express FLI1 (RPTEC)." (PMID 36793594, 2023). "To further address the functional contribution of EWSR1-ATF1 and its interplay with wt ATF1 we turned to primary pediatric mesenchymal stem cells (hpMSCs), a putative precursor model for a subset of human sarcomas." (PMID 35477713, 2022). "After treatment with Dox for 3 months, we found that mice containing Mpz-Cre allele developed CCS-like sarcomas, indicating that neural crest-derived cells are a cell of origin for EWS/ATF1-induced sarcomas." (PMID 31488818, 2019). "Accordingly, we next searched for candidate genes that are expressed in cell of origin for EWS/ATF1-induced sarcomas." (PMID 31488818, 2019). "We confirmed that sarcoma-derived iPSCs expressed similar levels of EWS/ATF1 with control ESCs and ETF-iPSCs (ear-tip fibroblast-iPSCs) upon Dox exposure." (PMID 31488818, 2019). "Histological analysis of sarcoma-iPSC mice shortly after EWS/ATF1 induction revealed that the abnormal cell growth often starts around the center of the abdominal wall." (PMID 31488818, 2019). "Collectively, we propose that Tppp3-expressing and Sox10/Krox20-negative neural crest-derived peripheral nerve cells are a cell of origin for EWS/ATF1-induced sarcomas, at least in this transgenic mouse model." (PMID 31488818, 2019). "Sarcoma-iPSC mice develop secondary sarcomas immediately after EWS/ATF1 induction, but only in soft tissue." (PMID 31488818, 2019). "EWS/ATF1 expression induces oncogene-induced senescence in most cell types in sarcoma-iPSC mice but prevents it in sarcoma cells." (PMID 31488818, 2019). "Consistent with the notion that EWS/ATF1-induced sarcomas arise from peripheral nerve cells, the early lesions express S100 protein." (PMID 31488818, 2019). "Taking advantage of the one-step and cell-type-specific nature of secondary sarcoma development in sarcoma-iPSC mice, we next attempted to identify a cell of origin for EWS/ATF1-induced sarcomas." (PMID 31488818, 2019). "Immunohistochemical analysis revealed that EWS/ATF1 is expressed in various organs and tissues of sarcoma-iPSC mice after Dox treatment (day 5)." (PMID 31488818, 2019). "Taken together, we propose that Tppp3-expressing and Sox10-negative neural crest-derived peripheral nerve cells are a cell of origin for EWS/ATF1-induced sarcomas." (PMID 31488818, 2019). "We also extracted 86 genes that increase after withdrawal of EWS/ATF1 expression in sarcoma cells (G1297) (criterion 3) (cut-off fold change; 5-fold)." (PMID 31488818, 2019).
sarcoma (continued). "Using this unique cancer model, we determined Tppp3-expressing peripheral nerve cells as an origin of EWS/ATF1-induced sarcomas, provided insights into the cell type specificity for cancer development." (PMID 31488818, 2019). "Mechanistically, we found that Ebf1-KRAB-expressing sarcoma cells exhibit a reduced enrichment of EWS/ATF1 at the super-enhancer when compared with the control NANOG-KRAB-expressing sarcoma cells." (PMID 31488818, 2019). "We also found that EWS/ATF1-induced sarcoma cell lines express several Schwann cell marker genes such as P75NTR, S100b, Mbp, Plp1, and Pmp22 in vitro." (PMID 31488818, 2019). "In sarcoma-iPSC mice, EWS/ATF1 induction resulted in microscopic sarcoma formation in 90% of mice (9/10) and macroscopic sarcoma development in 40% of mice (4/10) within 2 weeks." (PMID 31488818, 2019). "Interestingly, only one case exhibited the EWSR/CREB1 rearrangement, highlighting the predominance of the EWS/ATF-1 fusion in this specific sarcoma subtype." (PMID 38755643, 2024). "As with other sarcomas, each case of CCS is primarily driven by a single mutation particular to each tumour and for CCS genomic translocation results in the fusions of EWSR1 with ATF1 or, rarely, with CREB1." (PMID 33669307, 2021). "Conversely, SA β-gal-positive cells were increased by the withdrawal of EWS/ATF1 in sarcoma cells." (PMID 31488818, 2019). "To further confirm that Tppp3-expressing cells give rise to sarcomas, we also generated mice harboring Tppp3-CreERT2 allele and Rosa26-loxP-stop-loxP (LSL)-EWS/ATF1 allele (Rosa26Stop-E/A/Tppp3CreERT2) in which EWS/ATF1 can be induced in Tppp3-expressing cells upon tamoxifen treatment." (PMID 31488818, 2019). "Finally, four overlapping genes in three criteria were regarded as candidate marker genes for cell of origin for EWS/ATF1-induced sarcomas." (PMID 31488818, 2019). "Notably, we found a global downregulation of histone-coding genes in sarcoma-iPSC MEFs while they were generally upregulated in sarcoma cells upon EWS/ATF1 induction." (PMID 31488818, 2019). "We therefore hypothesized that unclassified neural crest derivatives in peripheral nerves may be a cell of origin for EWS/ATF1-induced sarcomas." (PMID 31488818, 2019). "Notably, EWS/ATF1 expression induced secondary sarcomas preferentially at the soft tissues, such as fascia, subcutaneous tissue, tissue adjacent to the tendon, and soft tissue outside the eyeballs." (PMID 31488818, 2019). "Consistently, EWS/ATF1 induced the expression of Ink4a, Arf, and Cdkn1a (p21) in sarcoma-iPSC MEFs." (PMID 31488818, 2019). "Moreover, consistent with our finding that EWS/ATF1 actively prevents premature senescence in sarcoma cells, SA β-gal-positive cells were increased in Ebf1-KRAB-expressing sarcoma cells." (PMID 31488818, 2019). "Therefore, we next performed detailed sequential histological analysis of the abdominal wall after EWS/ATF1 induction in sarcoma-iPSC mice together with ESC- and ETF-iPSC-derived mice." (PMID 31488818, 2019). "We next employed a genetic approach to determine a cell of origin for EWS/ATF1-induced sarcomas." (PMID 31488818, 2019). "In the current study, we found that the fusion mRNA could be detected in MVs from not only Ewing sarcoma cells (both type 1 and type 2 fusion of EWS/Fli-1), but also clear cell sarcoma cells which have another fusion gene (EWS/ATF-1)." (PMID 24124617, 2013). "Cheng and colleagues reported gene amplification of the chromosome region containing ATF1 could be a predictive biomarker for high sensitivity of sarcoma cell lines to several chemotherapeutics including alkylating agents and nucleoside analogues, but not bleomycin." (PMID 36860287, 2021).